MPP4 (MAGUK p55 scaffold protein 4)
Description:
May play a role in retinal photoreceptors development.
Synonyms: ALS2CR5; DLG6
Tractability: Antibody: its Gene Ontology location is reachable by antibodies, with medium confidence.
Gene: Protein-coding gene on chromosome 2 (201,644,870 to 201,698,694, reverse strand). Ensembl gene ENSG00000082126.
Subcellular location: Cytoplasm
Subcellular location (Human Protein Atlas): Cytosol; Actin filaments
Gene Ontology:
Molecular function: protein binding
Biological process: protein localization to synapse
Cellular component: adherens junction; cytosol; protein-containing complex; plasma membrane; basal part of cell; cone cell pedicle; cytoplasm; Golgi membrane; lateral plasma membrane; presynaptic membrane; rod spherule
Genetic constraint (gnomAD): Loss-of-function variants: 62 observed, 69.65 expected, observed/expected ratio (o/e) 0.89, 90% interval 0.73 to 1.1. The upper end of that interval is the gene's LOEUF score, 1.1, which puts it in group 4 of 6, group 1 being the genes least tolerant of losing a copy. Missense variants: 601 observed, 649.11 expected, observed/expected ratio (o/e) 0.93, 90% interval 0.87 to 0.99. Synonymous variants: 232 observed, 226.24 expected, observed/expected ratio (o/e) 1.03, 90% interval 0.92 to 1.14.
Homologues: Orthologues: chimpanzee MPP4 (99% identical), macaque MPP4 (98% identical), rabbit MPP4 (88% identical), dog MPP4 (83% identical), guinea pig MPP4 (83% identical), mouse Mpp4 (83% identical), rat Mpp4 (83% identical), pig MPP4 (82% identical), zebrafish mpp4a (48% identical), zebrafish mpp4b (41% identical), zebrafish mpp4l (41% identical), Drosophila melanogaster metro (34% identical), and 3 more. Paralogues in human: MPP7 (38% identical), MPP3 (35% identical), PALS1 (30% identical), PALS2 (28% identical), MPP2 (27% identical), CASK (27% identical), MPP1 (22% identical).
Diseases named in the same sentence as MPP4 in open-access papers:
MPP4 is named in the same sentence as 8 diseases in open-access papers, as found by Europe PMC text mining. Sharing a sentence is not in itself a finding about the gene and the disease. The quoted sentences say what the papers report.
leukemia (1 paper, 2022). A malignant (clonal) hematologic disorder, involving hematopoietic stem cells and characterized by the presence of primitive or atypical myeloid or lymphoid cells in the bone marrow and the blood. "This contrasts with adult bone marrow, where transformation of HSCs results in CD41+ leukemia, while transformation of MPP2, MPP3, and MMP4 cells results in both CD41+ and Gr1+ leukemias, with Gr1+ cells being more predominate in the transformed MPP3 and MPP4 populations." (PMID 36136600, 2022).
neuroblastoma (1 paper, 2021). Neuroblastoma (NB) is the most common solid, extracranial childhood tumor. "By contrast, GRM8 is an appealing drug target, as it is predominantly expressed in neurons and its activation has been reported to protect undifferentiated neuroblastoma cells against doxorubicin and the mitochondrial toxin MPP4+." (PMID 33661276, 2021).
retinal degeneration (1 paper, 2022). Degeneration of the retina. "Crb1, MPP4, PALS1, and aPKC, located in the AJs, are reported to be essential for photoreceptor morphogenesis and retinal degeneration." (PMID 36429029, 2022).
retinal disease (1 paper, 2025). "A majority of the significantly differentially expressed (FC > 2, FDR < 1%) genes show an increase in expression with higher glucose; these include genes involved in retina development (Neurod1, Casz1, and Crxos) or those associated with retinal disease (Impg1/2, Gucy2f, Mpp4, Arl6, and Rp1)." (PMID 40568109, 2025).
Stroke (1 paper, 2019). Sudden impairment of blood flow to a part of the brain due to occlusion or rupture of an artery to the brain. "However, literature retrieval results showed little evidences that other hub genes MPP4, RRM2, RRM2B, RRM1 and VCP contributed to the molecular mechanism of stroke prognosis." (PMID 31690277, 2019).
infection (2 papers, 2021 to 2022). The state of being infected such as from the introduction of a foreign agent such as serum, vaccine, antigenic substance or organism. "LKS+ cells (containing LT-HSC, MPP2, MPP3 and MPP4 subpopulations) significantly rose in the spleen of the 7-day PCA2-infected mice, and dropped at 14-day post PCA2 infection." (PMID 34975887, 2021).
tumor (1 paper, 2010). "Genes that were over-expressed in tumor versus normal brain in animals fed a SD (Serpinb1b, Cygb, Mpp4 and Ptgs2) were under-expressed in tumor from animals fed a KD." (PMID 20831808, 2010).
MPP4 also shares sentences with these, for which no sentence is quoted: schizophrenia (1 paper).